GSTM4 (glutathione S-transferase mu 4)
Description:
Conjugation of reduced glutathione to a wide number of exogenous and endogenous hydrophobic electrophiles. Catalyzes the conjugation of leukotriene A4 with reduced glutathione (GSH) to form leukotriene C4. Can also catalyze the transfer of a glutathionyl group from glutathione (GSH) to 13(S),14(S)-epoxy-docosahexaenoic acid to form maresin conjugate in tissue regeneration 1 (MCTR1), a bioactive lipid mediator that possess potent anti-inflammatory and proresolving actions.
Synonyms: GSTM4-4; GTM4
Tractability: Small molecule: it has a high-quality binding pocket. PROTAC: ubiquitination databases record sites on it.
Target class: Enzyme; Transferase
Gene: Protein-coding gene on chromosome 1 (109,656,099 to 109,665,496, forward strand). Ensembl gene ENSG00000168765.
Subcellular location: Cytoplasm
Subcellular location (Human Protein Atlas): Cytosol; Cytokinetic bridge; Microtubules; Primary cilium; Primary cilium tip
Pathways (Reactome):
Metabolism: Biosynthesis of maresin conjugates in tissue regeneration (MCTR); Glutathione conjugation
Gene Ontology:
Molecular function: enzyme binding; glutathione binding; glutathione transferase activity; leukotriene-C4 synthase activity; protein binding; protein homodimerization activity
Biological process: glutathione metabolic process; long-chain fatty acid biosynthetic process; xenobiotic catabolic process
Cellular component: cytoplasm; cytosol
Genetic constraint (gnomAD): Loss-of-function variants: 24 observed, 27.79 expected, observed/expected ratio (o/e) 0.86, 90% interval 0.62 to 1.21. The upper end of that interval is the gene's LOEUF score, 1.21, which puts it in group 5 of 6, group 1 being the genes least tolerant of losing a copy. Missense variants: 230 observed, 270.05 expected, observed/expected ratio (o/e) 0.85, 90% interval 0.76 to 0.95. Synonymous variants: 93 observed, 96.17 expected, observed/expected ratio (o/e) 0.97, 90% interval 0.82 to 1.15.
Homologues: Orthologues: chimpanzee GSTM4 (99% identical), mouse Gstm4 (87% identical), guinea pig Gstm2 (83% identical), dog GSTM4 (80% identical), rat Gstm4 (76% identical), tropical clawed frog gstm1 (66% identical), Caenorhabditis elegans gst-35 (25% identical), Caenorhabditis elegans gst-16 (25% identical), Caenorhabditis elegans gst-14 (24% identical), Caenorhabditis elegans gst-37 (24% identical), Caenorhabditis elegans gst-5 (24% identical), Caenorhabditis elegans gst-34 (23% identical), and 30 more. Paralogues in human: GSTM1 (87% identical), GSTM2 (83% identical), GSTM5 (83% identical), GSTM3 (72% identical), GSTP1 (28% identical), GSTA2 (25% identical), GSTA1 (24% identical), GSTA3 (24% identical), HPGDS (24% identical), GSTA4 (23% identical), GSTA5 (23% identical).
Diseases named in the same sentence as GSTM4 in open-access papers:
GSTM4 is named in the same sentence as 25 diseases in open-access papers, as found by Europe PMC text mining. Sharing a sentence is not in itself a finding about the gene and the disease. The quoted sentences say what the papers report.
Ewing sarcoma (6 papers, 2010 to 2024). A small round cell tumor that lacks morphologic, immunohistochemical, and electron microscopic evidence of neuroectodermal differentiation. "GSTM4 deficiency inhibited the progression of Ewing’s sarcoma and chemotherapy resistance." (PMID 35965498, 2022). "Additionally, in a small clinical series, increased expression of GSTM4 in primary Ewing tumors was associated with a lower overall survival." (PMID 24704979, 2012). "Our study also contributes novel mechanistic insight related to the drug resistance induced by GSTM4 in Ewing sarcoma." (PMID 25147782, 2014). "Knockdown of GSTM4 decreases oncogenic transformation and increases the sensitivity of Ewing sarcoma cells to chemotherapeutic drugs." (PMID 25147782, 2014). "In conclusion, GSTM4 transcripts constitute one of the major GST transcripts specifically expressed in Ewing sarcoma cells and tumors." (PMID 25147782, 2014). "Taken together, our studies point at GSTM4 as a key player and novel therapeutic target in Ewing sarcoma." (PMID 25147782, 2014). "Future studies in preclinical and clinical settings are required to fully evaluate the efficacy of targeting GSTM4 as a novel strategy to manage Ewing sarcoma." (PMID 25147782, 2014). "We previously found that knockdown of GSTM4 renders Ewing sarcoma cells more sensitive to etoposide." (PMID 25147782, 2014). "GSTM4 is required for oncogenic transformation and mediates resistance to chemotherapeutic drugs in Ewing sarcoma cells." (PMID 25147782, 2014). "Using a publicly available gene expression profile dataset of 19 Ewing sarcoma tumors, we again found that GSTM4 was one of the major GSTs expressed in Ewing sarcoma tumors." (PMID 25147782, 2014). "We complemented our NBDHEX inhibition studies with a second strategy that took advantage of high GSTM4 expression in Ewing sarcoma." (PMID 25147782, 2014). "High GSTM4 expression in primary tumors positively correlates with poor outcomes and increased resistance to etoposide and fenretinide in Ewing sarcoma." (PMID 25147782, 2014). "Molecular analyses in cellular models showed that JS-K inhibits the growth of Ewing sarcoma cells in a GSTM4-dependent fashion, and that this feature is recapitulated in in vivo settings." (PMID 25147782, 2014). "Here, we performed RNA-sequencing analyses of Ewing sarcoma cells and combined our results with publicly available datasets to demonstrate that GSTM4 is a major GST specifically expressed in Ewing sarcoma." (PMID 25147782, 2014). "Considering that etoposide resistance correlates with GSTM4 expression in Ewing sarcoma, the observed synergistic effects of NBDHEX and etoposide likely are due to inhibition of GSTM4." (PMID 25147782, 2014). "Our data suggest that GSTM4 is a novel therapeutic target for the treatment of high GSTM4-expressing Ewing sarcoma." (PMID 25147782, 2014). "GSTM4 belongs to a family of glutathione detoxifying enzymes and in patient-derived Ewing sarcoma cell lines, GSTM4 expression is necessary for maintenance of oncogenic transformation." (PMID 24704979, 2012). "When RNAi was used to knockdown GSTM4 levels in patient-derived Ewing's sarcoma cell lines, an increase in sensitivity to the chemotherapeutic drug, etoposide, was seen." (PMID 22523703, 2012). "Most recently, this same group combined transcriptional analysis, whole genome localization data, and RNA interference knockdown to identify glutathione S-transferase M4 (GSTM4) as a critical EWS/FLI target gene in Ewing's sarcoma." (PMID 20300555, 2010). "Additionally, the previous study has found that GSTM4 expression level affects the oncogenic and drug-resistant properties of Ewing’s sarcoma cells provides a relevant precedent for investigating the potential of GSTM4 as a therapeutic target in migraine." (PMID 39039470, 2024). "Here, we evaluated the potential utility of pharmacologically targeting GSTM4 in Ewing sarcoma." (PMID 25147782, 2014).
Ewing sarcoma (continued). "These combined observations suggest that GSTM4 is a promising novel target to treat Ewing sarcoma." (PMID 25147782, 2014). "We found that treatment with JS-K significantly reduced tumor growth (ANOVA Test p = 0.023) and increased overall survival (Mantel–Cox Test, p = 0.0002), strongly suggesting that this GSTM4 pro-drug has anti-tumorigenic effects that can be exploited for the treatment of Ewing sarcoma." (PMID 25147782, 2014). "To exploit our observation that GSTM4 expression is specifically up-regulated in Ewing sarcoma, we tested the effect of a GSTM4-activated anti-cancer agent, O2-(2,4-dinitrophenyl) 1-[(4-ethoxycarbonyl)piperazin-1-yl]diazen-1-ium-1,2-diolate or JS-K, on tumor growth and survival." (PMID 25147782, 2014). "Since GSTM4 is a major GST specifically expressed in EWS/FLI-driven Ewing sarcoma cells and tumors, drugs preferentially activated by GSTM4 (i.e., GSTM4 pro-drugs) may be attractive therapeutics to target drug-resistant Ewing sarcoma." (PMID 25147782, 2014). "We found very low GSTM4 expression in most non-Ewing sarcoma tumors and cell lines." (PMID 25147782, 2014). "This suggests that agents that disrupt the formation of GSTM4/ASK1 complexes or that reactivate the MAPK apoptotic pathway could potentially overcome drug resistance in Ewing sarcoma." (PMID 25147782, 2014). "We next asked whether GSTM4 is also highly expressed in Ewing sarcoma from human patients." (PMID 25147782, 2014). "Our previous observation that GSTM4 is required for oncogenic transformation and mediates etoposide resistance of Ewing sarcoma cells, led us to hypothesize that GSTM4 inhibitory agents might be cytotoxic and increase the sensitivity of Ewing sarcoma cells to etoposide." (PMID 25147782, 2014). "In addition, GSTM4 actively contributes to tumorigenesis and drug resistance in Ewing sarcoma." (PMID 25147782, 2014). "Taken together, our data suggest that GSTM4 binds to ASK1 and inhibits JNK activation and apoptosis induced by etoposide, thus increasing resistance of Ewing sarcoma cells to this commonly used cancer therapeutic agent." (PMID 25147782, 2014). "Pharmacological inhibition of GSTM4 activity using a pan GST inhibitor, 6-(7-nitro-2,1,3-benzoxadiazol-4-ylthio) hexanol (NBDHEX), significantly limited cellular proliferation and oncogenic transformation of Ewing sarcoma cells." (PMID 25147782, 2014). "We, and others, have observed that GSTM4 is a consistently up-regulated GST in Ewing sarcoma cell lines and Ewing, but not other, sarcomas from human patients." (PMID 25147782, 2014). "To determine whether this feature is unique to GSTM4 or common to other GST members, we characterized the expression profile of all known GST family members in patient-derived A673 Ewing sarcoma cells using RNA-seq." (PMID 25147782, 2014). "Notably, this GGAA microsatellite regulatory element is not present in any other GST promoters, suggesting that GSTM4 may be specifically expressed in Ewing sarcoma due to expression of the EWS/FLI oncoprotein in these malignancies." (PMID 25147782, 2014).
bladder cancer (2 papers, 2024 to 2025). "For all 3 proteins (GSTM1, GSTM4, and KLC1), there was strong evidence of colocalization (ie, PH4 ≥ 0.8), indicating that the protein and bladder cancer share a joint causal variant." (PMID 39898788, 2025). "NUCB1, GSTM4, and FGFR3 had associations with bladder cancer risk." (PMID 38684708, 2024). "For example, primary analyses identified higher GSTM4 was associated with a lower risk of bladder cancer [OR: 0.81, 95% CI: 0.74 to 0.89, PP4: 0.99] in main analyses, which was replicated in a combined bladder cancer GWAS from UK Biobank and Finngen cohorts [OR: 0.85, 95% CI: 0.77 to 0.93]." (PMID 38684708, 2024). "The associations of GSTM4 and KLC1 but not GSTM1 with bladder cancer risk were replicated (FDR < 0.1) using the corresponding cis-pQTLs from the Fenland study." (PMID 39898788, 2025).
lung carcinoma (2 papers, 2020 to 2023). "For example, the T2517C polymorphism in GSTM4 has been shown to be associated with an increased risk of lung cancer." (PMID 37020999, 2023). "Polymorphisms of the GSTM4 gene are associated with increased risk of lung cancer and could be used as a biomarker for the prediction of cisplatin response." (PMID 32539715, 2020).
prostate carcinoma (2 papers, 2015 to 2025). A carcinoma that arises from epithelial cells of the prostate gland. "Immunohistochemical information from the HPA database showed that higher staining of GSTM4, PLP1, and PTGS2 was found in normal prostate tissue, while higher staining of SLC27A2, SLC45A3, APOE, and ABCC4 was observed in prostate cancer tissue." (PMID 40861808, 2025).
steatosis (2 papers, 2013 to 2018). Increased lipid within the cytoplasm of cells. "Several studies reported that GSTM1, GSTM2, GSTM4 and GSTM5 mRNA levels are suppressed in patients with steatosis and NASH." (PMID 30080863, 2018). "GSTM2, GSTM4, and GSTM5 mRNA levels are expressed at lower levels in patients with steatosis and NASH." (PMID 23346097, 2013).
breast carcinoma (1 paper, 2013). "Using functional genomics we detected the overexpression of GSTM1 and GSTM4 in methotrexate-resistant MCF7 breast cancer cells, and determined that methotrexate was susceptible of glutathionylation by GSTs." (PMID 23675469, 2013).
breast tumor (1 paper, 2021). "The carcinogen metabolism genes, GSTM1, GSTM2, and GSTM4 are also located in this region and our eQTL analysis of breast tumor revealed highly significant associations between rs17024629 and these genes." (PMID 34234117, 2021).
cholestasis (1 paper, 2015). Impairment of the bile flow caused by obstruction within the liver, or outside the liver in the bile duct system. "Hepatic mRNA levels of GSTM1, GSTM2, and GSTM4 in patients with cholestasis were decreased to 38%, 46%, and 43% of control, respectively (p<0.05 for all), while GSTM3 and GSTM4 mRNA levels were not significantly changed." (PMID 25798860, 2015).
lung adenocarcinoma (1 paper, 2024). A carcinoma that arises from the lung and is characterized by the presence of malignant glandular epithelial cells. "We previously reported that loss of SMARCA4 in lung adenocarcinomas led to increased NRF2 signaling, including expression of the NRF2 targets HMOX1 and GSTM4." (PMID 38358974, 2024).
measles (1 paper, 2023). A highly contagious viral infection caused by the measles virus. "In measles, including six in whole blood (SOAT1, COLGALT2, AC021860.1, HCG11, METTL21B, and MRPL10), six in the lung tissue (GSTM4, PAQR6, RP11-617D20.1, SNX8, METTL21B, and ANKRD27), and two in the transformed fibroblast cells (CBWD2, and TSFM)." (PMID 37020999, 2023).
migraine (1 paper, 2024). "Our study found an association between increased GSTM4 expression and decreased migraine risk, which was also observed in MA and MO." (PMID 39039470, 2024). "The increased SD of circulating GSTM4 predicted by genes was found to be connected with a lower incidence of migraine (OR(95%CI) = 0.91(0.87–0.95); p = 6.98e-05), demonstrating convincing evidence of a correlation with the risk of migraine." (PMID 39039470, 2024). "Utilizing GSTM4 agonists could present an innovative and reliable approach to mitigate migraine risk." (PMID 39039470, 2024). "Therefore, we speculate that the decrease of GSTM4 expression causes the disruption of gut-brain axis and leads to migraine." (PMID 39039470, 2024). "The MR analysis of eQTL data showed that four drug targets (PROCR, GSTM4, SLC4A1, and TNFRSF10A) were significantly associated with migraine risk in both the FinnGen and UK Biobank cohorts." (PMID 39039470, 2024). "In summary, the available evidence supports the notion that both oxidative stress and the GST family member GSTM4 play an important role in the potential treatment and pathogenesis of migraine." (PMID 39039470, 2024). "In summary, this combination of different levels of Mendelian randomization and SMR analysis identified GSTM4 agonists as potentially effective treatment targets for migraine." (PMID 39039470, 2024). "This study identifies GSTM4 as a potential druggable gene and promising therapeutic target for migraine." (PMID 39039470, 2024). "To further determine the possibility of GSTM4 as a migraine treatment target, we used cis-pQTL data of GSTM4 from UKB-PPP for MR analysis." (PMID 39039470, 2024). "Further analyses provided additional validation for the possibility of GSTM4 as a migraine treatment target." (PMID 39039470, 2024). "To assess the genetic correlation, we performed LDSC analysis between GSTM4 and migraine." (PMID 39039470, 2024). "Thus, the GSTM4 may influence the development and progression of migraine through regulating the oxidative stress-related pathways." (PMID 39039470, 2024). "The gene GSTM4 consistently exhibited negative estimated effects in both cis-eQTL and cis-pQTL MR analyses, indicating a correlation between increased GSTM4 expression and decreased migraine risk." (PMID 39039470, 2024). "The results showed a significantly negative genetic correlation for GSTM4 with migraine (rg= -0.1977, p = 0.0145)." (PMID 39039470, 2024). "Consequently, an even more significant negative genetic connection was found between GSTM4 and migraine (rg = -0.4228, p = 0.0004)." (PMID 39039470, 2024).
sarcoma (1 paper, 2014). A usually aggressive malignant neoplasm of the soft tissue or bone. "We previously found that GSTM4 is an up-regulated target of the Ewing sarcoma oncoprotein EWS/FLI." (PMID 25147782, 2014). "We attempted to compare GSTM4 protein level in various sarcoma cell lines and tumors." (PMID 25147782, 2014).
cancer (3 papers, 2014 to 2025). A tumor composed of atypical neoplastic, often pleomorphic cells that invade other tissues. "One of these, GSTM4, was associated with a cancer-specific and lower risk [OR: 0.81, 95% CI: 0.74 to 0.89; PP4: 0.99]." (PMID 38684708, 2024).
GSTM4 also shares sentences with these, for which no sentence is quoted: tumor (3 papers); infection (2); acute leukemia (1); Anxiety (1); aortic aneurysm (1); hypertrophic cardiomyopathy (1); Immunodeficiency (1); larynx cancer (1); non-small cell lung carcinoma (1); pterygium (1); thyroid cancer (1); tinea (1).